C5orf47 (chromosome 5 open reading frame 47)
Synonyms: LOC133491
Tractability: No criterion of Open Targets' tractability assessment is met for any kind of drug.
Gene: Protein-coding gene on chromosome 5 (173,973,779 to 174,006,140, forward strand). Ensembl gene ENSG00000185056.
Genetic constraint (gnomAD): Loss-of-function variants: 12 observed, 6.18 expected, observed/expected ratio (o/e) 1.94, 90% interval 1.11 to 1.97. That is too few expected variants to judge how well the gene tolerates losing a copy. Missense variants: 191 observed, 139.4 expected, observed/expected ratio (o/e) 1.37, 90% interval 1.22 to 1.54. Synonymous variants: 88 observed, 63.55 expected, observed/expected ratio (o/e) 1.38, 90% interval 1.16 to 1.65.
Homologues: Orthologues: chimpanzee C5H5orf47 (97% identical), pig C5orf47 (61% identical), dog C5orf47 (58% identical), mouse 4930524B15Rik (45% identical), rat C10h5orf47 (43% identical).